ZIC2 (Zic family zinc finger 2)
Diseases named in the same sentence as ZIC2 in open-access papers (continued):
Sharing a sentence is not in itself a finding about the gene and the disease.
cancer (32 papers, 2015 to 2026). A tumor composed of atypical neoplastic, often pleomorphic cells that invade other tissues. "Elevated levels of ZIC2 are strongly associated with carcinogenesis and the self-renewal of cancer cells." (PMID 40520016, 2025). "Overexpression of ZIC2 was intimately associated with the invasion, metastasis, and self-renewal of cancer cells." (PMID 38304730, 2024). "Zinc-finger of the cerebellum 2 (Zic2) is widely implicated in cancers, but the role of Zic2 in tumorigenesis is bilateral." (PMID 34099631, 2021). "ZIC2 gene expression was associated with the prognosis of pan-cancer in PrognoScan." (PMID 33665207, 2021). "Importantly, high expression of ZIC2 is closely associated with tumorigenesis and self-renewal of cancer cells." (PMID 32922547, 2020). "K-M curve that high expression of ZIC2 was associated with poor PFI time in eight types of cancer (ACC, KICH, KIRC, KIRP, LGG, LIHC, MESO, and SARC) and only showed that the low expression of ZIC2 was related to poor PFI time in cancer of LUSC." (PMID 33665207, 2021). "We comprehensively analyzed the differential expression of the ZIC2 gene and its relationship with the prognosis of cancer patients using bioinformatics databases in the present study." (PMID 33439969, 2021). "Taken together, these findings strongly indicated that ZIC2 can be used as a biomarker to judge the prognosis of various cancers." (PMID 33665207, 2021). "Some studies have reported that ZIC2 functions as an oncogene in cancers, whereas others have revealed that the decreased expression of ZIC2 promotes tumorigenesis." (PMID 33439969, 2021). "The discrepancy in its effects in different cancers makes it difficult to define the role of Zic2 in proliferation." (PMID 34099631, 2021). "We first used Oncomine to investigate the expression of ZIC2 gene across cancers compared with corresponding normal tissues." (PMID 33665207, 2021). "We also obtained the expression of ZIC2 gene in cancer and normal tissues in 33 cancer samples from the TCGA database." (PMID 33665207, 2021). "ZIC2 overexpression have been reported in variety of cancer types including prostate, suggesting it to be an oncogenic transcription factor." (PMID 30197753, 2018). "ZIC2 overexpression has been reported in epithelial ovarian tumors samples and is correlated strongly with the clinical course of cancer." (PMID 30197753, 2018). "Among the significant transcription factors ZIC2 was also overexpressed in a cancer-specific fashion in all datasets studied here." (PMID 30197753, 2018). "One of the possible mechanisms is targeting ZIC2, a potential oncogene for many types of cancer." (PMID 38139235, 2023). "The role of ZIC2 in cancer varies among different cancer types." (PMID 37479694, 2023). "The high expression levels of ZIC2 and JUNB were positively correlated and linked to a poor outcomes in NPC patients, implying that ZIC2, JUNB, and CD163 could be utilized as prognostic markers for NPC and as therapeutic targets for cancer immunotherapy." (PMID 37479694, 2023). "Recent studies have reported that ZIC2 functions as an oncogene in various cancers." (PMID 33439969, 2021). "Current studies have shown that ZIC2 plays an oncogene role in various cancers." (PMID 33665207, 2021). "Loss of ZIC2 expression was associated with adverse outcome and correlated with significantly shorter time to biochemical recurrence in all cancers, independent of ERG and PTEN." (PMID 31640781, 2019). "Within ERG fusion-negative cancers, ZIC2 expression was also strongly associated with 6q15 and 5q21 deletions (p < 0.001)." (PMID 31640781, 2019). "Zinc-finger protein of the cerebellum (ZIC) 2, identified as a target gene of miR-129-5p in the present study, is the vertebrate homologues of the Drosophila odd-paired (OPA) gene, including ZIC1, ZIC2, ZIC3, ZIC4 and ZIC5, and has been implicated in multiple diseases including cancer." (PMID 31649488, 2019).
cancer (continued). "However, in most cancers, Zic2 acts as a transcriptional activator promoting tumorigenesis." (PMID 34099631, 2021). "and it may indicate that ZIC2 may act as an oncogenic driver in human cancer." (PMID 33665207, 2021). "Zic family member 2 (ZIC2) has been reported to be overexpressed in LUAD and promotes cancer stemness." (PMID 34232917, 2021). "ZIC2, as transcription factor (TF), behaved as the other core pluripotent TFs (SOX2, NANOG, c-MYC) in cancer stem cells." (PMID 32922547, 2020). "Finally, there is enough information on the role of CDKN2A, ZIC2, ELAVL2, and HS6ST2 genes in cancer." (PMID 40361484, 2025). "In summary, our study implies that ZIC2 induces M2 TAM polarization, at least in part through regulation of JUNB/MCSF and that ZIC2, JUNB, and CD163 can be utilized as prognostic markers for NPC and as therapeutic targets for cancer immunotherapy." (PMID 37479694, 2023). "ZIC2 promotes OCT4 transcription and cancer stemness through NuRF." (PMID 38028543, 2023). "Zinc finger protein ZIC2 (ZIC2) has been found to interact with TCF7L2, enabling it to act as a Wnt/β-catenin signaling inhibitor, thus regulating Wnt signaling which has been found to be upregulated in several cancers." (PMID 33114107, 2020). "ZIC2 could activated the PI3K/AKT signal pathway, which played a vital role in TSCC, as it promotes viability, migration, and invasion of cancer cells." (PMID 31141819, 2019). "PTGS2, FN1, CXCL9, CXCL10, ZIC2 e OVOL1 podem desempenhar alguns papéis no carcinoma nasofaríngeo." (PMID 27765529, 2017). "RT-PCR results showed that the expression levels of CCL19, CD24, and ZIC2 were significantly higher in the MCF-7, ZR-75-1, and SK-BR-3 cell lines compared to the reference MCF-10A group, whereas the transcription level of CEBPD was significantly lower in the cancer cell lines (p < 0.05)." (PMID 40895068, 2025). "At present, there is no comprehensive study on the prognostic significance of ZIC2 in pan-cancer." (PMID 33665207, 2021). "ZIC2 e OVOL1 podem funcionar no carcinoma nasofaríngeo almejando-se de maneira significativa os genes suprarregulados (como o PTGS2, FN1, CXCL9 e CXCL10) na rede reguladora de fator de transcrição - genes diferencialmente expressos (p.ex., ZIC2→PTGS2 e OVOL1→CXCL10)." (PMID 27765529, 2017).
ZIC2 also shares sentences with these, for which no sentence is quoted: endometrial cancer (3 papers); congenital heart disease (2); genetic disease (2); holoprosencephaly 5 (2); myopia (2); osteosarcoma (2); ovarian carcinoma (2); prostate adenocarcinoma (2); Alzheimer disease (1); autism (1); B-cell lymphoma (1); bipolar disorder (1); brain tumors (1); cardiovascular disorder (1); craniorachischisis (1); Dandy-Walker malformation (1); head and neck cancer (1); Huntington disease (1); infections during (1); liposarcoma (1); lymph node metastasis (1); Macrocephaly (1); malignant pleural mesothelioma (1); Micrognathia (1); microphthalmia (1); movement disorder (1); neuroblastoma (1); neurodevelopmental disorder (1); neurological diseases (1); ocular hypertelorism (1).
A further 7 diseases each share a sentence with ZIC2 in 1 paper.